RNASEK-C17orf49 (RNASEK-C17orf49 readthrough)
Synonyms: BAP18; C17orf49
Gene: Protein-coding gene on chromosome 17 (7,012,635 to 7,017,520, forward strand). Ensembl gene ENSG00000161939.
Genetic constraint (gnomAD): Loss-of-function variants: 14 observed, 22.54 expected, observed/expected ratio (o/e) 0.62, 90% interval 0.41 to 0.97. The upper end of that interval is the gene's LOEUF score, 0.97, which puts it in group 4 of 6, group 1 being the genes least tolerant of losing a copy. Missense variants: 273 observed, 295.73 expected, observed/expected ratio (o/e) 0.92, 90% interval 0.83 to 1.02. Synonymous variants: 115 observed, 114.37 expected, observed/expected ratio (o/e) 1.01, 90% interval 0.86 to 1.17.